TRBV5-6 (T cell receptor beta variable 5-6)
Description:
V region of the variable domain of T cell receptor (TR) beta chain that participates in the antigen recognition. Alpha-beta T cell receptors are antigen specific receptors which are essential to the immune response and are present on the cell surface of T lymphocytes. Recognize peptide-major histocompatibility (MH) (pMH) complexes that are displayed by antigen presenting cells (APC), a prerequisite for efficient T cell adaptive immunity against pathogens. Binding of alpha-beta TR to pMH complex initiates TR-CD3 clustering on the cell surface and intracellular activation of LCK that phosphorylates the ITAM motifs of CD3G, CD3D, CD3E and CD247 enabling the recruitment of ZAP70. In turn ZAP70 phosphorylates LAT, which recruits numerous signaling molecules to form the LAT signalosome. The LAT signalosome propagates signal branching to three major signaling pathways, the calcium, the mitogen-activated protein kinase (MAPK) kinase and the nuclear factor NF-kappa-B (NF-kB) pathways, leading to the mobilization of transcription factors that are critical for gene expression and essential for T cell growth and differentiation. The T cell repertoire is generated in the thymus, by V-(D)-J rearrangement. This repertoire is then shaped by intrathymic selection events to generate a peripheral T cell pool of self-MH restricted, non-autoaggressive T cells. Post-thymic interaction of alpha-beta TR with the pMH complexes shapes TR structural and functional avidity.
Synonyms: TCRBV5S2; TRBV56; TCRBV5S6
Tractability: Antibody: UniProt places it where antibodies can reach, with medium confidence; UniProt predicts a signal peptide or a membrane-spanning region; its Gene Ontology location is reachable by antibodies, with medium confidence.
Gene: T-cell receptor variable (V) gene on chromosome 7 (142,500,028 to 142,500,534, forward strand). Ensembl gene ENSG00000211728.
Subcellular location: Cell membrane
Gene Ontology:
Biological process: cell surface receptor signaling pathway
Cellular component: plasma membrane
Homologues: Paralogues in human: TRBV5-5 (91% identical), TRBV5-7 (89% identical), TRBV5-4 (89% identical), TRBV5-3 (79% identical), TRBV5-1 (72% identical), TRBV9 (62% identical), TRBV13 (58% identical), TRBV11-2 (49% identical), TRBV7-9 (48% identical), TRBV11-1 (47% identical), TRBV11-3 (47% identical), TRBV7-7 (47% identical), and 39 more.